SLC7A11 (solute carrier family 7 member 11)
Diseases named in the same sentence as SLC7A11 in open-access papers (continued):
Sharing a sentence is not in itself a finding about the gene and the disease.
breast cancer (continued). "Notably, SLC7A11 overexpression is observed in various human cancers, including lymphoma, leukemia, squamous cell carcinoma, breast cancer, glioblastoma, and pancreatic ductal adenocarcinoma (PDAC)." (PMID 36552652, 2022). "SLC7A11 over-expression promotes lipo-ROS accumulation in MCF-7 breast cancer cells." (PMID 34059009, 2021). "Our results thus far suggest that xCT positive breast cancer cells—Those expressing high levels of both SLC7A11 and SLC3A2—Are able to drive GPX4 expression through the selenocysteine biosynthesis pathway, and also are able to resist lipid prooxidant-induced death." (PMID 33672555, 2021). "Recently, SLC7A11 has been found to play an important role in tumor growth, progression, and metastasis in various types of cancer including pancreatic tumors, glioblastomas, breast cancer, esophageal tumors, and ovarian cancer." (PMID 34446045, 2021). "Consequently, we concluded that the lidocaine promoted ferroptosis by miR-382-5p/SLC7A11 axis in ovarian and breast cancer cells." (PMID 34122108, 2021). "Moreover, in multivariate analysis, high expression of SLC7A11 was an independent prognostic factor for OS of breast cancer." (PMID 35252218, 2021). "Moreover, Slc7a11 has been reported to regulate several tumorigenic events, such as breast cancer apoptosis, poor glioblastoma survival, and cancer glucose metabolism and dependence." (PMID 33433832, 2021). "In breast cancer, SLC7A11 is important for the proliferation of TNBC." (PMID 29562706, 2018). "In previous studies, mice with deficiencies in SLC1A5, SLC6A14, and SLC7A11, which have been reported to be upregulated in breast cancer, were found to be viable and fertile and to have no abnormal phenotypes." (PMID 29562706, 2018). "In a mouse model with brain metastasis from breast cancer, SLC7A11 was found to be upregulated." (PMID 29562706, 2018). "SLC7A11 is also responsible for distant metastasis of breast cancer." (PMID 29562706, 2018). "Drugs inhibiting SLC7A11 gene could have great therapeutic potential, as demonstrated by in vitro and vivo studies in breast cancer and resistant head and neck cancer cells using the SLC7A11 inhibitors." (PMID 30558624, 2018). "Some amino acid transporters, including SLC1A5, SLC6A14, SLC7A5, and SLC7A11, may be promising targets for the treatment of breast cancer since they modulate tumor growth, metastasis, treatment response, and prognosis of breast cancer." (PMID 29562706, 2018). "Furthermore, we identified Nrf2, an important transcription factor for the SLC7A11 gene, as a factor that limits the ability of breast cancer cells to utilize glutamine instead of glucose." (PMID 28429737, 2017). "Indeed, examination of panels of human breast cancer cell lines have found that xCT/SLC7A11 promotes glutamate secretion, providing further evidence that xCT/SLC7A11 can promote glutamine catabolism in cell types beyond NSCLC." (PMID 28826492, 2017). "Furthermore, overexpression of miR-26b induces apoptosis in MCF-7 breast cancer cells by targeting SLC7A11." (PMID 23374284, 2013). "Since overexpression of SLC7A11 and SLC3A2 also reduced sensitivity of ER+ breast cancer cells to Fulvestrant treatment, we hypothesized that drug targeting SLC7A11 and SLC3A2 should have efficacy against endocrine-resistant breast tumors by inducing ferroptosis." (PMID 39833180, 2025). "Hence, metformin inhibited UFMylation of SLC7A11 in breast cancer." (PMID 39247188, 2024). "Finally, we performed biological assays to determine whether KCTD10 or USP18 coordinates with SLC7A11 to regulate the cell viability and clonogenic survival of breast cancer cells." (PMID 38959043, 2024). "In breast cancer, inhibition of SLC7A11 could induce ferroptosis." (PMID 38102129, 2023).
breast cancer (continued). "Recently, one study deserves attention that SIRT3 may play a protective role in the glucose-deprivation-induced cell death of breast cancer cells by regulating the xCT expression, also known as solute carrier family 7 member 11 (SLC7A11), to balance the ROS levels." (PMID 35832551, 2022). "SLC7A11 immunotargeted therapies—such as the SLC7A11-targeted DNA vaccination, a virus-like particle immunotherapy targeting the SLC7A11 protein, and an anti-SLC7A11 viral vaccine based on the bovine herpesvirus 4 vector —also impede the progression of breast cancer by inhibiting SLC7A11." (PMID 35804831, 2022). "Notably, SLC7A11 has been frequently observed in various malignant tumours, including lymphomas, leukaemias, Kaposi’s sarcoma, squamous-cell carcinomas/epithelial carcinomas, breast cancer, glioblastoma (GBM), and pancreatic cancers (PDAC)." (PMID 35804831, 2022). "Six ferroptosis-related genes (SLC7A11, GPX4, FTH1, NQO1, NFE2L2, SQSTM1) demonstrated consistent upregulation across all breast cancer subtypes, with higher expression observed in more aggressive tumors." (PMID 42074090, 2026). "In conclusion, our data reveal that targeting estrogen-regulated SLC7A11 and SLC3A2 enhances ferroptosis in ER+ breast cancer, offering a novel therapeutic option for patients with ER+ breast cancer, particularly those with endocrine resistance." (PMID 39833180, 2025). "Our study demonstrated that ERα binds to the ERE present in the promoter regions and enhances the transcription of SLC7A11 and SLC3A2, inhibiting ferroptosis and contributing to the growth of ER+ breast cancer cells." (PMID 39833180, 2025). "In breast cancer, decreased cystine levels in the tumor microenvironment remodel the expression of KCTD10 and USP18, regulating SLC7A11 stability and subsequently cystine metabolism." (PMID 41330917, 2025). "In breast cancer, FMRP catalyzes N6-methyladenosine (m6A) modification of Solute Carrier Family 7 Member 11 (SLC7A11) mRNA and interacts with Heterogeneous Nuclear Ribonucleoprotein M (hnRNPM) to mediate SLC7A11-S splicing, promoting ferroptosis resistance." (PMID 40563420, 2025). "SLC7A11 is upregulated in breast cancer, particularly in those with poor prognosis, such as ER-negative, claudin-low, and TNBC, which show higher levels of SLC7A11 mRNA and protein expression." (PMID 39973065, 2025). "In a breast cancer model established subcutaneously in BALB/c female mice, vaccination with anti-SLC7A11 formulations not only inhibited the growth kinetics of primary tumors but also reduced lung colonization." (PMID 39973065, 2025). "q-PCR analysis demonstrated that estrogen significantly increased the mRNA levels of SLC7A11 and SLC3A2 in ER+ breast cancer cells." (PMID 39833180, 2025). "Together, these results indicate that ERα is recruited to the ERE-containing promoters in SLC7A11 and SLC3A2, thereby enhancing SLC7A11 and SLC3A2 expression in response to estrogen stimulation in ER+ breast cancer cells." (PMID 39833180, 2025). "It has been demonstrated that SLC1A5, SLC6A14, SLC7A11, SLC3A1, SLC7A5, SLC38A2, and SLC38A5 are significantly expressed in breast cancer cells." (PMID 39973065, 2025). "Since ERα transcriptionally upregulated SLC7A11 and SLC3A2 expression, we believe that estrogen/ERα inhibits ferroptosis mainly through the xc−-GPX4 axis in ER+ breast cancer." (PMID 39833180, 2025). "While SLC7A11 correlated with FIN AUCs pan-cancer, its correlation specifically in breast cancer is poor (also when comparing to CTRP data)." (PMID 39310772, 2024).
breast cancer (continued). "Trastuzumab can increase the expression of circular RNA BGN in breast cancer cells BT474 and SKBR3, enhance the deubiquitination and expression of SLC7A11, inhibit ferroptosis, induce drug resistance in cancer tissue, an effect that can be reversed by erastin." (PMID 39664391, 2024). "Building on this foundation, a recent study introduced a novel prognostic model for breast cancer, that integrates four ferroptosis-related genes (CISD1, ALOX15, CARS1, and SLC7A11)." (PMID 39867656, 2024). "Breast cancer patients with lymph node metastasis, distant metastasis or late TNM stage luminal-like subtype (stage III&IV), have higher levels of SLC7A11 and vimentin." (PMID 39543094, 2024). "The UFMylation of solute carrier family 7 member 11 (SLC7A11), the cysteine transporter, has a crucial impact on breast cancer tumorigenesis." (PMID 39259506, 2024). "FOXQ1 knockdown increases breast cancer ferroptosis and inhibits oncogenesis via the FOXQ1/circ_0000643/miR-153/SLC7A11 axis." (PMID 38778030, 2024). "Consistently, the high levels of SLC7A11 and USP18, and low levels of KCTD10 are coordinately coupled with decreased cystine levels in breast cancer tissues, indicating the pathological relevance." (PMID 38959043, 2024). "Metformin down-regulates SLC7A11 expression by inhibiting UFMylation modification of SLC7A11, promoting ferroptosis in TNBC cancer cells, reducing breast cancer volume in vivo, and achieving better results when used in combination with sulfasalazine." (PMID 39664391, 2024). "For mechanism of circ_0022382, we revealed that knockdown of circ_0022382 inhibited the proliferation and migration of breast cancer cells via sponging let-7a-5p, down-regulated p-AKT and SLC7A11, promoted the occurrence of disulfidptosis." (PMID 39868374, 2024). "To investigate the relationship between SLC7A11 expression and EMT progress during carcinogenesis, we performed immunohistochemistry in collected paraffin sections of tumors of 101 patients with breast cancer and matched adjacent normal tissues." (PMID 39543094, 2024). "The inclusion of these 8 genes (ALOX15, CHAC1, CISD1, CS, SLC7A11, EMC2, G6PD, and ACSF2) is highly valuable for prognostic prediction in breast cancer patients." (PMID 39867656, 2024). "miR-324-3p and miR-382-5p induce ferroptosis by targeting GPX4 and SLC7A11’s 3’-UTR, inhibiting breast cancer progression." (PMID 39664391, 2024). "Compared to normal tissues, expression of SLC7A11 and USP18 was increased, whereas expression of KCTD10 was decreased in multiple types of human cancers, including breast cancer." (PMID 38959043, 2024). "As Keap1-Nrf2 plays an important role in cellular resistance to ferroptosis 37, 38, We focused on changes in SLC7A11-GSH-GPX4, an important ferroptosis resistance system, and ferroptosis levels after disrupting miR-141-3p in breast cancer cells." (PMID 39308683, 2024). "After exposure of breast cancer cells to ionizing radiation, interactions between NEDD4L and SLC7A11 increase, followed by SLC7A11 ubiquitination and degradation, ultimately inducing ferroptosis in breast cancer cells." (PMID 38027016, 2023). "The high expression of disulfidptosis genes (e.g., SLC3A2, RPN1, BRK1, ACTR2, ACTR3, SLC7A11, and NCKAP1) in the KM analysis of breast cancer indicated the poor prognosis of patients." (PMID 38035071, 2023). "For example, cystine antiporter xCT (also known as SLC7A11) can potentiate secretion of glutamate to promote the invasive behavior of colorectal cancer (CRC) and breast cancer." (PMID 36998464, 2023). "Functionally, alloimperatorin directly decreases the expression levels of SLC7A11 and GPX4, thereby inhibiting the growth and invasion of breast cancer cells." (PMID 37488128, 2023). "Experimental studies have shown that CDKN2A, PSAT1, HMGB1, ELAVL1, and SLC7A11 were up-regulated in TNBC, ASNS and LAMP2 were up-regulated in breast cancer and CAV1 was down-regulated in breast cancer, and HELLS was up-regulated in other tumors." (PMID 36568247, 2022).
breast cancer (continued). "Sulfasalazine has been found to trigger breast cancer cell ferroptosis via the repression of GPX4 and SLC7A11 expressions and an increase in TFR1 and DMT1 expressions, particularly in cells with low estrogen receptor (ER) expression." (PMID 35805124, 2022). "SLC7A11 and FPN1 expression was upregulated in trastuzumab-resistant HER2-positive breast cancer cells compared to parental cells." (PMID 35562334, 2022). "Lidocaine induces the ferroptosis of ovarian and breast cancers by increasing miR-382-5p and decreasing SLC7A11, while ketamine induces ferroptosis by targeting the KAT5/GPX4 axis in breast cancer cells." (PMID 35805124, 2022). "Metformin increases Fe2+ and lipid ROS, reduces the stability of SLC7A11 by inhibiting the ultrafiltration process of SLC7A11, and metformin combined with SAS can synergistically activate ferroptosis and inhibit the growth of breast cancer cells." (PMID 36467032, 2022). "Circ-BGN binds to OTUB1 and SLC7A11 and inhibits ferroptosis to confer resistance to trastuzumab in HER-2+ breast cancer." (PMID 36467032, 2022). "A previous study showed that some ferroptosis-related genes had the potential to be promising treatment targets in breast cancer, such as iron, ACSL4, GPX4, SLC7A11 and SLC3A." (PMID 33672990, 2021). "To clarify the role of UFM1 in ferroptosis regulation by metformin, we first detected the expression of SLC7A11 and UFM1 in different breast cancer cell lines." (PMID 34162423, 2021). "High expression of SLC7A11 was significantly correlated with the poor OS and RFS in bladder carcinoma, breast cancer, kidney renal papillary cell carcinoma, liver hepatocellular carcinoma, and pancreatic ductal adenocarcinoma." (PMID 34722530, 2021). "SLC7A11 is a subunit of system xc−, and CD44 has been reported to regulate activity of system xc− in breast cancer." (PMID 33292585, 2020). "Previous studies reported that miR-26b mimics triggered apoptosis of human breast cancer MCF7 cells, and SLC7A11 was identified as a direct target of miR-26b." (PMID 23374284, 2013). "Interestingly, a recent study showed that CDK4/6 inhibitors blocked SLC7A11 expression by inhibiting SP1 binding to the SLC7A11 promoter and induced ferroptosis in luminal A breast cancer cells." (PMID 39833180, 2025). "Furthermore, analysis of the TCGA dataset indicated a weak positive correlation between the mRNA levels of SLC7A11 and ESR1 in luminal A and luminal B subtypes of breast cancer." (PMID 39833180, 2025). "Our study implicates that targeting the estrogen-dependent system xc−, specifically SLC7A11 and SLC3A2, with IKE through induction of ferroptosis in ER+ breast cancer cells, should offer a new therapeutic option for patients with ER+ breast cancer, particularly those with endocrine resistance." (PMID 39833180, 2025). "For instance, direct pharmacological inhibition of GPX4’s enzymatic activity with agents like RSL3, or depletion of GSH by blocking the upstream transporter SLC7A11 with inhibitors such as erastin, both lead to a sharp increase in intracellular LOOH levels in breast cancer cells." (PMID 41008615, 2025). "Additionally, the protein levels of SLC7A11 and SLC3A2 were found to be positively correlated with ERα protein levels in ER+ breast cancer cell lines." (PMID 39833180, 2025). "Clinical analysis confirms the negative correlation between METTL3 and SLC7A11 in breast cancer tissues." (PMID 39800682, 2025). "Since the combination of overexpressing SLC7A11 and SLC3A2 partially alleviated ferroptosis induced by ERα knockdown, it is also possible that estrogen/ ERα regulates ferroptosis through xc−-GPX4 independent pathway in ER+ breast cancer cells." (PMID 39833180, 2025). "Moreover, SLC7A11 and SLC3A2 levels were elevated in endocrine-resistant breast cancer cells and tumors." (PMID 39833180, 2025). "Moreover, elevated mRNAs levels of SLC7A11 and SLC3A2 were correlated to decreased overall survival and relapse-free survival rates of breast cancer." (PMID 39833180, 2025).
breast cancer (continued). "To investigate whether SLC7A11 and SLC3A2 are involved in ERα-regulated ferroptosis, we examine the effects of knocking down SLC7A11 and SLC3A2 using two different shRNAs in ER+ breast cancer cells." (PMID 39833180, 2025). "Protein levels of GPX4, SLC7A11, and SLC3A2 in four luminal breast cancer cell lines (MDAMB415, ZR75-1, MCF7, and CAMA1), four basal breast cancer cell lines (MDAMB436, MDAMB231, HCC1937, and HCC1806), and one normal breast epithelial cell line (MCF10A) were concordant with mRNA expression." (PMID 37596261, 2023). "Consistently, the real-time PCR analysis confirmed that 4HC treatment led to a significant increase in Hmox-1 and Slc7a11 mRNA levels at an early stage (within 6 h) in the murine glioblastoma cell lines GL261, CT-2A, and KR-158 and the 4T1 murine breast cancer." (PMID 35264971, 2022). "Watanabe’ group demonstrated that the inhibition of SLC7A11 including SAS treatment may overcome resistance to vorinostat by accumulating ROS and inducing ferroptosis in human breast cancer cell and colon cancer cell." (PMID 36105219, 2022). "In addition, the elevated expression of SLC7A11 was also observed in LLC and A549 lung cancer cells, HepG2 liver cancer cells and MDA-MB-231 breast cancer cells." (PMID 35053507, 2022). "Next, utilizing publicly available databases, our bioinformatics analysis showed that there was a significant negative correlation between the expression of SLC7A11 and the prognosis of breast cancer patients, but not UFM1." (PMID 34162423, 2021). "In 414 breast cancer cases, both KLF4 and SLC7A11 mRNA levels were negatively related to patients’ post progression survival (PPS); that is, the higher the KLF4 or SLC7A11 mRNA expression level, the lower the survival rate after progression." (PMID 34040532, 2021). "Similar to HCC cells, we have also found that YAP/TAZ and ATF4 repress ferroptosis by inducing SLC7A11 expression in other cancer cell types, including HT1080 fibrosarcoma and MDA‐MB‐231 breast cancer cells, suggesting a potentially high generality of the results." (PMID 34664408, 2021). "Most breast cancer cells can survive under glutamine restriction; however, a subgroup of TNBC exhibits features of a true glutamine auxotroph, requiring cysteine import via SLC7A11." (PMID 29562706, 2018). "In addition, estrogen receptor 1 can activate SLC7A11 expression, and estrogen receptor 1 knockdown increases ferroptosis in malignant cells; also, NEDD4L ubiquitinates SLC7A11 in estrogen receptor-positive breast cancer cells during radiation." (PMID 38778030, 2024). "Our correlation study using the human breast cancer tissues also revealed a negative association between KCTD10 and SLC7A11, and a positive association between USP10 and SLC7A11 at both mRNA and protein levels, indicating a pathological relevance of our finding." (PMID 38959043, 2024). "Under either cystine-enriched or cystine-starved condition, SLC7A11 knockdown inhibited, whereas KCTD10 knockdown promoted cell viability and clonogenic survival, suggesting that SLC7A11 promotes cell viability and survival, whereas KCTD10 inhibits them in breast cancer cells." (PMID 38959043, 2024). "However, the protein levels of SLC7A11 in ER+ breast cancer cell lines are quite lower than in ER− breast cancer cells, suggesting that SCRIB-SLC3A2 complex mainly targets SLC7A5 in ER+ breast cancer cells." (PMID 35501367, 2022). "Although downregulation of SLC7A11 inhibits GSH synthesis and induces oxidative stress, it leads to the increased expression of the efflux transporter P-glycoprotein (P-gp), also called multidrug resistance protein 1, MDR1, and therefore induces a drug-resistant phenotype in breast cancer cells." (PMID 33401748, 2021). "Additionally, we did not observed any significant changes in SLC7A11 expression in NSC/JQ1 alone or combination treatment in breast cancer cells." (PMID 34803511, 2021).